S100P (S100 calcium binding protein P)
Diseases named in the same sentence as S100P in open-access papers (continued):
Sharing a sentence is not in itself a finding about the gene and the disease.
tumor (continued). "Immunohistochemically, tumor cells were positive for Vimentin (mesenchyme), CK7, CK19, MUC-1, MUC-5AC, MUC-6, S-100p (focal), Ki-67 (12%), and negative for Inhibin-α, ER, CK20, CEA, and MUC-2." (PMID 33592896, 2021). "In areas of white matter adjacent to tumour, occasional astrocytes were seen to stain with anti-S100P antibody; however, morphology and staining of serial sections with GFAP clarified that these were not tumour cells, thus avoiding any false positives." (PMID 27100728, 2016). "The mean tumour tissue versus mean normal tissue Histoscore for MUC1 was 193 vs. 48, while for S100P, KOC and mesothelin, the mean tumour tissue versus mean normal tissue Histoscores were 165 vs. 0.3, 150 vs. 0.5 and 115 vs. 4 respectively." (PMID 25071419, 2014). "The localization of S100P and RAB25 in tumor tissues was similar to that in cultured cells (data not shown)." (PMID 20142997, 2010). "Finally, analysis of TCGA PanCancer Atlas PDAC datasets demonstrated poor prognosis in patients with high S100P and low S100PBP expression, suggesting that S100PBP is a novel tumour suppressor gene with potential clinical utility." (PMID 37794133, 2023). "Cross striations may be appreciated and these tumours are positive for SMA, Desmin, and Myogenin, and are negative for S100P on immunohistochemical stains." (PMID 34514564, 2022).
cancer (126 papers, 2005 to 2025). A tumor composed of atypical neoplastic, often pleomorphic cells that invade other tissues. "S100P, a member of S100 family of small calcium‐binding proteins, has been implicated in various cancers, and has been recognized for its diagnostic value in AML." (PMID 39688413, 2025). "Firstly, we comprehensively analyzed the S100P landscape in cancer, including its expression, survival, and clinical associations." (PMID 37853345, 2023). "The only gene associated with the risk of LUAD in the present study was S100P, which had been identified as associated with the risk of several other types of cancer and in the promotion of metastasis." (PMID 36177001, 2022). "S100P protein is a potent inducer of metastasis in a model system, and its presence in cancer cells of patients is strongly associated with their reduced survival times." (PMID 34680103, 2021). "For instance, in cancers associated with the colon and pancreas, S100P induced cancer invasion, migration, and proliferation through the stimulated receptor for advanced glycation end-products (RAGE) receptor." (PMID 33923162, 2021). "S100P has been reported to interact with a number of proteins both extracellularly and intracellularly, and its over expression in varied human cancers has been associated with disease progression, acquisition of chemoresistance and poor prognosis." (PMID 31767037, 2019). "Further genes are TFF1, known to induce metastasis and to regulate cancer-stroma interactions and S100P, which is associated with cell proliferation and survival, and is expressed in about 50% of pancreatic lesions." (PMID 29675033, 2018). "S100P proteins have been found in a variety of tumors and are associated with metastasis, making them a key interest in cancer research." (PMID 24821384, 2014). "A panel of KOC, S100P and mesothelin with at least 2 biomarkers positive achieved almost perfect diagnostic accuracy in the differentiation of carcinoma from normal tissue." (PMID 25071419, 2014). "Overexpression of S100P has been detected in several cancers such as breast, colon, prostate, pancreatic and lung carcinomas, and the protein has been functionally implicated in carcinogenic processes." (PMID 18282279, 2008). "Several studies have elucidated the role of S100P as a diagnostic marker in cancers." (PMID 39284282, 2024). "S100P was also reportedly causing resistance in cancer cells to chemotherapy." (PMID 37927641, 2023). "S100P, a member of the S100 protein family, has been implicated in various cancers." (PMID 37853345, 2023). "Increased immunohistochemical levels of S100P are associated with markedly reduced survival times of patients with breast, hepatocellular, early stage non-small cell lung, colon, and ovarian cancers." (PMID 34680103, 2021). "This suggests that S100P plays a pivotal role in integrin-mediated cancer progression, and that the inhibition of S100P may be a promising target for diagnostic and therapeutic interventions against metastatic events." (PMID 26320193, 2015). "Existing data collectively indicate that S100P is overexpressed in many types of cancer and that it may potentially serve as a diagnostic, prognostic and predictive marker and possibly also as a target of molecular therapy." (PMID 25585623, 2015).
cancer (continued). "Genes and proteins, including S100P, which confer a metastatic phenotype upon the benign Rama 37 cells in this system, have subsequently been shown to be associated also with reduced patient survival time when they are found in the cancer cells of human patients." (PMID 34680103, 2021). "S100P emerged as a top candidate for functional studies as it showed strong association with TzR both in vivo and in vitro studies, it is highly upregulated in many cancer types, and it belongs to the S100 family of proteins with well-documented roles in tumorigenesis." (PMID 27449296, 2016). "Thereafter, we focused on S100P, a secretory factor, due to its importance in cancer growth and metastatic progression." (PMID 40420099, 2025). "ROC analysis further confirmed the predictive power of S100P for 1-year, 3-year, and 5-year survival in these cancers." (PMID 40224483, 2025). "Significant differences were observed in protein concentration levels between cancer and inflammatory lesions for S100P, PIGR, C1QBP, TAGLN, and CNN1 (P ═ 0.0006, P ═ 0.0032, P ═ 0.0008, P < 0.0001, P ═ 0.0094, respectively) as shown in." (PMID 39284282, 2024). "A significant correlation was observed for S100P mRNA expression levels between cancer and inflammatory lesions (P ═ 0.0458)." (PMID 39284282, 2024). "The overexpression of S100P promotes cancer progression and metastasis through extracellular signaling via the RAGE receptor or through intracellular interaction with ezrin." (PMID 37583701, 2023). "S100P is an EF-hand calcium-binding protein and its overexpression has been detected in many cancer types." (PMID 37583701, 2023). "The potent G-quadruplex experimental anticancer drug QN-302 down-regulates a number of cancer-related genes, in particular S100P." (PMID 37970888, 2023). "How S100P promotes cellular motility and invasion in different cells has been put forward in the context of cancer migration/invasion." (PMID 37627296, 2023). "In the cancer cell lines, statistically significant correlations were found between S100P and S100A8 (R = 0.91), and S100A11 (R = 0.73)." (PMID 37627239, 2023). "Other cancer-related interaction partners of S100P are interleukin-11 and interferon-β, and their binding can modulate local inflammation processes and the host immune response." (PMID 35597866, 2022). "Secondly, circ_0092314 has been shown to induce EMT in this type of cancer through sponging miR-671 and releasing S100P from its inhibitory effects." (PMID 35317077, 2022). "Immunohistochemical results revealed that these S100P + SPP1 + cells were mostly present in the invasive regions of cancer nodules in certain iCCAphl cases." (PMID 35347134, 2022). "Expression of S100P in most pancreatic (83.3%) and liver (54.5%) cancers showed moderate to intense cytoplasmic and nuclear staining." (PMID 35831362, 2022). "S100P, on the other hand, includes the genesis of cancer and plays an important role in cancer progression." (PMID 36613714, 2022). "Many of these DEGs, including CGA, CDKN1A, FN1, CLIC3, and S100P, have been reported to play essential roles in cancer progression." (PMID 35521536, 2022). "In carcinoma cell lines, S100P and YAP1 expression levels were both increased under the same treatment, whereas S100P was apparently up- or downregulated after YAP1 knockdown or overexpression." (PMID 36187124, 2022). "S100P is a small molecular weight calcium binding protein that is involved in cancer occurrence and progression, and is highly up-regulated during the mid-secretory phase of normal fertile endometrium." (PMID 34215278, 2021). "In humans, on 4p16, the S100P gene is mapped; a relatively “young” gene with a range of various functions, from cellular behavior to the development of cancer." (PMID 34063545, 2021).
cancer (continued). "Research suggested that S100P can stimulate the progression of a variety of cancers and acts as an oncogene." (PMID 33968130, 2021). "S100P is involved in diverse biological processes, including cellular calcium signaling and cancer progression." (PMID 34200172, 2021). "Several studies have investigated the effect of recombinant S100P on cancer cell proliferation and survival, and an S100P concentration of 10–100 nM or more was found to show a significant effect." (PMID 34200172, 2021). "Recent findings suggest that S100P protein expression is upregulated in a range of cancers, consisting of the colon, pancreatic, breast, and lung carcinomas." (PMID 33923162, 2021). "We will also discuss the possible advantages of developing new drug targets to inhibits S100P’s role in cancer tissue." (PMID 33923162, 2021). "S100P is expressed in various organs, including the pancreas, breast, and prostate, and shows highly increased expression in most cancers, suggesting that S100P can be used as a prognostic marker." (PMID 34200172, 2021). "There is a correlation between overexpression of S100P and resistance to cyclophosphamide, etoposide, methotrexate, and mitoxantrone in different cancer cell lines." (PMID 33042844, 2020). "The fluorescence signal intensities of S100P in these two cancer cell lines were significantly stronger than those of primary endometrial epithelial cells and stromal cells." (PMID 32883230, 2020). "S100P is also involved in drug response in different cancer types, either by increasing chemoresistance or enhancing chemosensitivity." (PMID 33042844, 2020). "Recently, we reported a highly specific interaction between IFN-β and S100P lowering IFN-β cytotoxicity to cancer cells (Int J Biol Macromol." (PMID 33322098, 2020). "S100P has also been reported in several other cancers, including colon, breast, lung, ovarian, nasopharyngeal and cervical cancers." (PMID 32707527, 2020). "A similarly low Kd of 0.3 nM was recently reported for IFN-β binding to monomeric S100P protein, a cancer-related member of the S100 protein family." (PMID 33322098, 2020). "The protein has shown some promise as a druggable target, with S100P’s cancer-promoting effects being suppressed through siRNA silencing and small molecule downregulation of S100P expression." (PMID 32707527, 2020). "The compounds identified in this study represent a diverse set of scaffolds, providing proof of concept of the wider potential to design novel small molecule therapies that will have a functional and selective effect against S100P-expressing cancers." (PMID 32707527, 2020). "The transcriptional regulation of S100P expression is highly dependent on the type of cancer and tissue." (PMID 33005177, 2020). "Further, we observed that cancer cell lines with E-cadherin dysfunction displayed a significant upregulation of S100P expression when compared to those with wild-type E-cadherin and the stomach tissue." (PMID 31767037, 2019). "In the majority of cancers, S100P has been evaluated as a potential biomarker for detection of disease and a potential target for therapeutic intervention given its absence in the respective healthy tissues." (PMID 31767037, 2019). "In OV-CCA tissues, CD44v9 was primarily expressed in the cell membrane and moderately in the cytoplasm of CCA cells, and S100P mostly appeared in the cytoplasm and nucleus of cancer cells." (PMID 30402042, 2018). "Accumulating evidences have suggested a link between S100P expression and progression of various types of cancers." (PMID 30558666, 2018). "We also showed that S100P facilitates the therapy-induced senescence and supports the clonogenic survival of cancer cells." (PMID 26967060, 2016). "Conversely, the S100P silencing suppresses the ability of cancer cells to survive the DNA damage and form colonies." (PMID 26967060, 2016).
cancer (continued). "There was no significant variation in BM staining for the S100 proteins by primary cancer (Fisher's exact test for S100P, P=0.279, and S100A4, P=0.135)." (PMID 27100728, 2016). "All six pre-specified cancer genes (IL8, IL1, SAT, OAZ1, DUSP1 and S100P) were up-regulated in cancer versus control patients with from nearly twofold to over threefold higher levels (p<0.01 for all based on delta Cq values)." (PMID 27411053, 2016). "S100P promotion of cancer progression via its specific role in cell proliferation, survival, angiogenesis, and metastasis in human cancers has been reported." (PMID 26009899, 2015). "Most studies have indicated that overexpression of S100P correlates with proliferation, tumorigenesis regulation, invasion, metastasis, and cancer cell motility." (PMID 26009899, 2015). "Our study showed that SOX9 regulation of S100P promotes cancer cell migration and invasion as well as inducing EMT." (PMID 26009899, 2015). "To investigate the role of ZEB1 on S100P-mediated cancer migration and EMT, we inhibited ZEB1 by siRNA transfection, then assessed the expression of EMT markers and cell migration." (PMID 26320193, 2015). "Knockdown of integrin α7 prevents cell migration, EMT (N-cadherin upregulation), and FAK activation in S100P overexpressing cancer cells, suggesting that S100P promotes cancer progression by binding integrin α7 and the FAK/AKT signaling pathway." (PMID 26320193, 2015). "Conversely, overexpression of S100P in CL1-0 and A549 cells causes EMT and increased cancer movement and invasion potential." (PMID 26320193, 2015). "Overexpression of S100P has been demonstrated in several forms of cancer, including pancreas, breast, prostate, lung, and colon." (PMID 24821384, 2014). "S100P has been shown to aid in cancer progression through its roles in cell proliferation, survival, angiogenesis, and metastasis." (PMID 24821384, 2014). "The calcium-binding protein S100P is expressed in a variety of human cancer cells and is important in cancer cell growth and invasion." (PMID 23785431, 2013). "Binding of the Ca2+ activated S100P homodimer to RAGE has been shown to promote cancer cell proliferation via the ERK1/2 and NFκB signaling pathways." (PMID 22417809, 2012). "For example, S100P has been shown to promote cancer cell growth by interacting with key regulators." (PMID 41404073, 2025). "Moreover, the pan-cancer analysis underscores the broader clinical relevance of S100P, offering new insights into its role in immune modulation and cancer prognosis." (PMID 40224483, 2025). "Both SFN and S100P have been shown to be involved in cancer progression." (PMID 39628446, 2024). "In addition, overexpression of S100P significantly promoted cancer cell migration and invasion in A549 and H460 cells." (PMID 38342601, 2024). "S100P has also been reported as a biomarker for various cancer types." (PMID 37627907, 2023). "For example, S100P is ever reported to be involved in the aggressive properties of cancer cells and associated with poor prognosis; TNS4 is associated with cancer cell motility and migration, whose high expression can indicate poor prognosis." (PMID 37303949, 2023). "S100P plays a crucial role in cancer cell survival and chemotherapy resistance." (PMID 37315289, 2023). "Moreover, cellular analysis of S100P expression among thirty different types of cancer cells showed a significant trend of high expression in PAAD." (PMID 37853345, 2023). "S100P also increases cancer cell resistance to chemotherapy by inhibiting apoptosis." (PMID 37315289, 2023). "S100P serves as a potential therapeutic target in cancer treatment." (PMID 37583701, 2023). "The binding of S100P to the receptor of advanced glycation end products (RAGE) can trigger intracellular signalling cascades that eventually lead to increased survival of cancer cells, as well as to higher cell proliferation and migration." (PMID 35597866, 2022).